MCEMP1 (mast cell expressed membrane protein 1)
Synonyms: C19orf59; MGC132456
Tractability: Antibody: its Gene Ontology location is reachable by antibodies, with high confidence; UniProt predicts a signal peptide or a membrane-spanning region; the Human Protein Atlas places it where antibodies can reach. PROTAC: its protein half-life has been measured.
Gene: Protein-coding gene on chromosome 19 (7,677,088 to 7,679,833, forward strand). Ensembl gene ENSG00000183019.
Subcellular location: Membrane
Subcellular location (Human Protein Atlas): Plasma membrane
Pathways (Reactome):
Immune System: Neutrophil degranulation
Gene Ontology:
Molecular function: identical protein binding; protein binding
Cellular component: membrane; plasma membrane; specific granule membrane; tertiary granule membrane
Genetic constraint (gnomAD): Loss-of-function variants: 17 observed, 27.9 expected, observed/expected ratio (o/e) 0.61, 90% interval 0.42 to 0.91. The upper end of that interval is the gene's LOEUF score, 0.91, which puts it in group 3 of 6, group 1 being the genes least tolerant of losing a copy. Missense variants: 200 observed, 200.95 expected, observed/expected ratio (o/e) 1, 90% interval 0.89 to 1.12. Synonymous variants: 87 observed, 77.43 expected, observed/expected ratio (o/e) 1.12, 90% interval 0.94 to 1.34.
Homologues: Orthologues: chimpanzee MCEMP1 (97% identical), macaque MCEMP1 (77% identical), dog MCEMP1 (51% identical), guinea pig Mcemp1 (47% identical), mouse Mcemp1 (47% identical), rat Mcemp1 (45% identical).
Diseases named in the same sentence as MCEMP1 in open-access papers:
MCEMP1 is named in the same sentence as 41 diseases in open-access papers, as found by Europe PMC text mining. Sharing a sentence is not in itself a finding about the gene and the disease. The quoted sentences say what the papers report.
Sepsis (13 papers, 2020 to 2026). Sepsis is defined as life-threatening organ dysfunction caused by a dysregulated host response to infection. "Machine learning algorithms identify 3 diagnostic genes - CD177, LDHA, and MCEMP1 - consistently highly expressed in sepsis patients." (PMID 39029061, 2024). "This study represents the inaugural exploration of the causal association between MCEMP1 levels and the risk of sepsis, employing 2-sample MR analysis." (PMID 39029061, 2024). "By conducting an MR analysis with these SNPs and applying the IVW method, we found a statistically significant association (OR = 1.376, 95% CI = 1.011–1.873, P = .042), suggesting a positive causal link between MCEMP1 and sepsis risk." (PMID 39029061, 2024). "We employed machine learning methods (LASSO, RF, and SVM-RFE) to select 3 diagnostic genes (CD177, LDHA, and MCEMP1) to investigate potential sepsis biomarkers." (PMID 39029061, 2024). "In conclusion, this study presents potential sepsis diagnostic biomarkers, highlighting the genetic association of MCEMP1 with sepsis for insights into early diagnosis." (PMID 39029061, 2024). "MR studies suggest that elevated serum MCEMP1 levels may increase the risk of sepsis and that there is a causal relationship." (PMID 39029061, 2024). "MR analysis reveals a positive causal relationship between MCEMP1 and sepsis risk." (PMID 39029061, 2024). "MCEMP1, in particular, demonstrated a positive causal relationship with sepsis risk." (PMID 39029061, 2024). "In summary, CD177, LDHA and MCEMP1 were identified as diagnostic biomarkers for sepsis." (PMID 39029061, 2024). "Finally, we investigated the causal relationship between MCEMP1 and sepsis using MR studies." (PMID 39029061, 2024). "The effect of MCEMP1 on QIVs-induced immunity in elderly populations remains to be elucidated, although growing studies demonstrated its diagnostic capacity on the progression of stroke, and the promotion effect of its high expression on inflammation and sepsis." (PMID 33343577, 2020). "In previous studies, we observed that MCEMP1 was elevated in a mouse sepsis model and a human LPS-treated macrophage model." (PMID 40599778, 2025). "We used MCEMP1 as the exposure factor and sepsis as the outcome, incorporating 14 SNPs as instrumental variables." (PMID 39029061, 2024). "One of these DEGs, MCEMP1, for instance, is highly expressed in sepsis, its down-regulation inhibited the inflammation of septic mice." (PMID 38166628, 2024). "Previous research has highlighted the importance of MCEMP1 in sepsis, viral infection, and a potential useful prognostic tool in stroke patients." (PMID 35178459, 2022). "Downregulation of NEAT1 has restricted immune response in mouse model of sepsis and induced T cell apoptosis through modulating miR-125/MCEMP1 axis." (PMID 34804042, 2021). "At the same time, blocking the overexpression of the MCEMP1 gene could potentially serve as a treatment alternative for patients suffering from severe sepsis or septic shock." (PMID 40599778, 2025). "Previous research has revealed that MCEMP1 plays a crucial role in sepsis and viral infections." (PMID 38028617, 2023). "It was determined, for the first time, that the high expression of MCEMP1 in peripheral blood might serve as a prognostic biomarker of stroke and that it plays a role in the pathogenesis of inflammation and sepsis." (PMID 35047008, 2021). "A total of 1389 DEGs such as NOV, SEPT9, XIST, ESYT1 were upregulated in sepsis, whereas 1657 DEGs such as S100A9, IRAK3, MCEMP1, TLR5, CD177 were downregulated." (PMID 41542228, 2026). "In this study, three core genes (CD163, MCEMP1 and RETN) that lead to sepsis death in children were screened out, providing a new understanding of the lethal mechanism of sepsis in children and a promising new therapeutic approach." (PMID 40599778, 2025). "The results revealed a significant up-regulation of MCEMP1, CD177, and LDHA in the sepsis groups compared to the healthy groups (P < .05)." (PMID 39029061, 2024).
Sepsis (continued). "By leveraging bioinformatics analysis and machine learning algorithms, we systematically identified five immune-related candidate hub genes (CLEC5A, KLRB1, LCN2, MCEMP1, and MMP9) and provided a nomogram for diagnosing ROP with sepsis." (PMID 38028617, 2023). "verified that the miR-125-mediation MCEMP1 suppression could decrease the sera levels of TNF-α, IL-1β, and IL-6, and the programmed cell death facilitated the T leukomonocyte activity, hence attenuating the immune activity of sepsis mice." (PMID 37359526, 2023).
Stroke (8 papers, 2020 to 2024). Sudden impairment of blood flow to a part of the brain due to occlusion or rupture of an artery to the brain. "C19orf59 (or MCEMP1) was originally identified as a Mast cell-associated protein and is a peripheral blood biomarker for patients with stroke." (PMID 32318053, 2020). "As a biomarker, it has been suggested that MCEMP1 expression in peripheral blood may contribute to the diagnosis of stroke and serve as a biomarker of a 1-month stroke prognosis." (PMID 35378772, 2022). "Second, we did not compare and analyze laboratory follow-up data and consider the biomarkers that are not routinely used in laboratory tests, such as Mast cell expressed membrane protein 1, a new prognostic and diagnostic biomarker for stroke." (PMID 35387672, 2022). "In dataset GSE16561, with the threshold of p < 0.05, CLEC4D, GPR97, MCEMP1, and TSPAN14 were significantly upregulated in the stroke group (The platform GPL6883 did not explore FPR2's expression)." (PMID 35075378, 2022). "In addition, elevated MCEMP1 has been recently reported as a negative prognostic marker in COVID-19 as well as other diseases such as stroke, thus is possible that MCEMP1 participates in fibrosis post injury." (PMID 38189137, 2024).
COVID-19 (6 papers, 2022 to 2024). A disease caused by infection with severe acute respiratory syndrome coronavirus 2. "The most consistent differentially regulated genes in peripheral blood of severe COVID-19 patients were MCEMP1, HLA-DRA and ETS1 across the 7 transcriptomics datasets." (PMID 36801619, 2023). "Among the top differentially regulated transcripts, MCEMP1 was upregulated by an average of 3.62-fold in severe COVID-19 patients compared to mild COVID-19 patients." (PMID 36801619, 2023). "Since severe COVID-19 is characterised by increased C Reactive Protein (CRP) and lymphopenia, which were used in several COVID-19 clinical severity scores, we correlated the abundance of MCEMP1, ETS1 and HLA-DRA transcripts to CRP and lymphocyte counts." (PMID 36801619, 2023). "Of the 52 well-described IPF signature genes in our study, only 7 were upregulated in COVID-19 patients with NP, whereas in the SP group, only few genes, namely PLBD1, S100A12, and MCEMP1, were upregulated." (PMID 39205185, 2024). "Single cell RNA sequencing revealed that the upregulation of MCEMP1 and downregulation of HLA-DRA transcripts in severe COVID-19 subjects were seen in CD14+ immune cell subsets, which are primarily myeloid lineage cells." (PMID 36801619, 2023). "Future prospective studies will also be needed to validate the sensitivity and specificity of using MCEMP1 and HLA-DRA expression levels in predicting severe COVID-19." (PMID 36801619, 2023). "In particular, MCEMP1 and HLA-DRA were found to be differentially expressed in severe COVID-19 patients as early as four days from nadir of respiratory function." (PMID 36801619, 2023). "To assess the informativeness of MCEMP1, ETS1 and HLA-DRA throughout each phase of COVID-19, we examined the temporal dynamics of these transcripts before and after the nadir of respiratory function from the same study cohort." (PMID 36801619, 2023). "Elevated MCEMP1 and reduced HLA-DRA gene expression in CD14+ cells during the early phase of disease are prognostic of severe COVID-19." (PMID 36801619, 2023). "The comparative transcriptomics analysis indicated MCEMP1, ETS1 and HLA-DRA as the most promising candidates in discriminating severe vs mild COVID-19 outcomes." (PMID 36801619, 2023). "Based on our systematic review and temporal characterisation of gene expression profiles, we ascertained that the induction of MCEMP1 and the downregulation of HLA-DRA gene expression was most reliable for early prediction of severe COVID-19." (PMID 36801619, 2023). "This highlights that the early expansion of myeloid-derived suppressor cell gene signatures, particularly MCEMP1 and HLA-DRA, can be an early prognostic biomarker for COVID-19 disease severity." (PMID 36801619, 2023). "Taken together, these findings highlight that MCEMP1 and HLA-DRA could be useful early prognostic biomarker for severe COVID-19 but likely limited for prognosis of severe influenza and dengue." (PMID 36801619, 2023). "We used a total of 7 publicly available RNAseq datasets, comprising of a total of 140 severe and 181 mild COVID-19 patients collected during the acute phase of SARS-CoV-2 infection, and uncovered that the top differential genes included MCEMP1, ETS-1 and HLA-DRA." (PMID 36801619, 2023). "Indeed, the combination of both MCEMP1 and HLA-DRA expression levels was able to distinguish patients who subsequently developed severe vs mild COVID-19." (PMID 36801619, 2023). "Hence, peripheral blood MCEMP1 and HLA-DRA gene expression levels could be useful for early triaging of patients before severe COVID-19 disease progression." (PMID 36801619, 2023). "As the upregulation of MCEMP1 and downregulation of HLA-DRA are characteristic of myeloid-derived suppressor cells (MDSCs), the results indicated that an early expansion of MDSCs could be involved in severe COVID-19 progression and pathogenesis." (PMID 38257728, 2023).
COVID-19 (continued). "Future studies that investigate MCEMP1 gene regulation, function and protein expression in monocytes after SARS-CoV-2 infection could thus shed valuable insights into the early molecular events that lead to severe COVID-19." (PMID 36801619, 2023). "Unlike MCEMP1, which was exclusively differentially expressed in CD14+ cells, reduced expression of HLA-DRA could be detected more broadly across other myeloid cells, B cells, T cells, NK cells and platelets, indicating a global suppression of antigen presentation in severe COVID-19 patients." (PMID 36801619, 2023).
gastric cancer (6 papers, 2022 to 2025). A primary or metastatic malignant neoplasm involving the stomach. "were the first to report that the MCEMP1 gene had a significant association with the prognosis of gastric cancer." (PMID 37359526, 2023). "To evaluate the association between MCEMP1 expression and prognosis of gastric cancer, we assessed the interaction between MCEMP1 expression levels and patient survival using TCGA-related data." (PMID 35378772, 2022). "To investigate the influence of MCEMP1 on migration and aggression of gastric cancer cells, we assayed EMT-related markers (EMT is associated with tumor invasion and metastasis) at the protein expression level." (PMID 35378772, 2022). "MCEMP1, a trans-membrane protein expressed by immune cells, is associated with TIIC and the inflammatory response of gastric cancer." (PMID 40458391, 2025). "The findings at the protein level demonstrated that MCEMP1 knockdown in gastric cancer cells resulted in the downregulation of N-cadherin and upregulation of E-cadherin, implying involvement in the EMT process." (PMID 35378772, 2022). "Next, we identified an essential role for MCEMP1 in promoting proliferation, colony formation, migration, and invasion of gastric cancer cells." (PMID 35378772, 2022). "Further, we found a close relationship between MCEMP1 and poorer prognosis of gastric cancer by prognostic analysis." (PMID 35378772, 2022). "Based on the fact that MCEMP1 is expressed by mast cells as a transmembrane protein and the multifunctional role of mast cells in cancer, this has led to an interest in the role of MCEMP1 in gastric cancer progression." (PMID 35378772, 2022). "In another study on gastric cancer, MCEMP1 was also involved in constructing a predictive model as a factor on regulatory T cells." (PMID 35378772, 2022). "To further analyze the possible biological processes involved in MCEMP1 in gastric cancer, we proposed enriching the data of TCGA by GO, KEGG." (PMID 35378772, 2022). "In in vitro experiments, modification of MCEMP1 can affect the invasiveness and metastasis of gastric cancer cells by regulating EMT, in which TLR4/NOD2/NF-κB was involved." (PMID 35378772, 2022). "In particular, it has been demonstrated that MCEMP1 may affect the proliferation, migration, and invasion of gastric cancer cells by regulating epithelial-to-mesenchymal transition." (PMID 38189137, 2024). "In our study, overexpression of MCEMP1 increased the expression of N-cadherin but decreased the expression of E-cadherin, also suggesting that MCEMP1 may mediate gastric cancer metastasis through EMT." (PMID 35378772, 2022). "In cellular experiments, the invasion and metastasis of gastric cancer cells could be promoted by regulating the rise of MCEMP1 expression." (PMID 35378772, 2022). "In particular, a negative trend of MCEMP1 expression in relation to overall survival (OS) was observed in gastric cancer patients." (PMID 35378772, 2022).
idiopathic pulmonary fibrosis (3 papers, 2023 to 2025). Idiopathic pulmonary fibrosis (IPF) is a nonneoplastic pulmonary disease that is characterized by the formation of scar tissue within the lungs in the absence of any known cause. "Previous research has indicated that, in addition to being associated with asthma, MCEMP1 is also related to various inflammatory lung diseases, such as idiopathic pulmonary fibrosis (IPF)." (PMID 41567222, 2025). "Mast-cell expressed membrane protein-1 (MCEMP1) is higher in patients with idiopathic pulmonary fibrosis (IPF) with an increased risk of death." (PMID 38189137, 2024). "In addition to pulmonary fibrosis, a recent study demonstrated that MCEMP1 deficiency blunted SCF-induced peritoneal mast cell proliferation in vitro and lung mast cell expansion in vivo." (PMID 38189137, 2024). "Second, we did not validate our results in vivo; yet we provide strong in vitro evidence for the role of MCEMP1 in pulmonary fibrosis." (PMID 38189137, 2024). "Our study provides both human data and strong in vitro evidence for the role of MCEMP1 in the pathogenesis of pulmonary fibrosis." (PMID 38189137, 2024). "Our report is also the first study providing mechanistic insights for the role of MCEMP1 in pulmonary fibrosis and one of the few studies identifying the mechanistic role of MCEMP1 in general." (PMID 38189137, 2024). "In comparison to OVA-challenged Mcemp1+/+ mice, OVA-challenged Mcemp1–/– mice also exhibited less collagen deposition in the lungs, indicating reduced lung fibrosis." (PMID 37041174, 2023). "Thus, we used a monocytic cell line (THP-1 cells) for our mechanistic studies and demonstrated that MCEMP1 is a transcriptional target of TGFβ, a key mediator of pulmonary fibrosis." (PMID 38189137, 2024). "Our results suggest that MCEMP1 may regulate the migration and transition of monocytes to monocyte-derived alveolar macrophages during pulmonary fibrosis development and progression." (PMID 38189137, 2024). "Here we aimed to establish the mechanistic role of MCEMP1 in pulmonary fibrosis." (PMID 38189137, 2024). "Although we studied peripheral blood gene expression changes predictive of IPF mortality, we did not study the cellular source and the mechanisms of MCEMP1 in the pathogenesis of pulmonary fibrosis." (PMID 38189137, 2024).
asthma (2 papers, 2023 to 2025). "Mechanistically, our in vivo study indicates that MCEMP1 promotes the expansion of mast cells, which contributes to severe lung inflammation in asthma." (PMID 37041174, 2023). "In summary, this study advances our understanding of the MCEMP1-mediated regulation of KIT receptor for mast cell proliferation and asthma development, and further offer molecular insights into the development of new therapies for allergic and inflammatory lung diseases." (PMID 37041174, 2023).
autoimmune disease (2 papers, 2024). A disorder resulting from loss of function or tissue destruction of an organ or multiple organs, arising from humoral or cellular immune responses of the individual to their own tissue constituents. "Hence, MCEMP1, based upon its concentration or level in many immune-related and inflammatory disorders, can also be used as an attractive biomarker for the diagnosis, prevention, and treatment of autoimmune disorders." (PMID 38956704, 2024). "The relationship between GMPR, DNAH8, MCEMP1, and autoimmune diseases has not yet been reported." (PMID 38639399, 2024).
chronic asthma (2 papers, 2023 to 2024). An asthma that is characterized by the development of persistent airway inflammation and recurrent attacks of breathlessness and wheezing, which vary in severity and frequency. "Mcemp1-deficient mice had decreased airway inflammation and lung impairment in mouse models of chronic asthma." (PMID 38189137, 2024). "Mcemp1-deficient mice exhibit reduced airway inflammation and lung impairment in chronic asthma mouse models." (PMID 37041174, 2023). "Overall, Flexivent lung functional examinations and 4DMedical imaging results indicate that MCEMP1 deficiency leads to reduced lung inflammation and improved lung function in OVA-induced chronic asthma model." (PMID 37041174, 2023). "We developed a chronic asthma mouse model in Mcemp1–/– mice of the C57BL/6 strain, based on previous studies that utilized C57BL/6-KitW-sh mast cell-deficient mice to demonstrate the critical role of mast cells in the OVA-induced chronic asthma model." (PMID 37041174, 2023). "At 12 weeks later, Mcemp1–/– recipients were subjected to OVA-induced chronic asthma model." (PMID 37041174, 2023). "In this work, we elucidate the pathological activity of MCEMP1-mediated amplification of KIT receptor signaling in mast cell proliferation, and its impact on the progression of airway inflammation and lung function impairment in a chronic asthma mouse model." (PMID 37041174, 2023).